HDAC2 (histone deacetylase 2)
Diseases named in the same sentence as HDAC2 in open-access papers (continued):
Sharing a sentence is not in itself a finding about the gene and the disease.
lymphedema (1 paper, 2017). Excess fluid collection in tissues, causing swelling. "Our results demonstrate that endothelial inactivation of ubiquitously expressed Hdac3, but not Hdac1 or Hdac2, in mice causes embryonic lethality, failure of blood-lymph separation, lymphedema, and defects in both lymphatic and lymphovenous valves." (PMID 29035278, 2017).
lymphoblastic lymphoma (1 paper, 2025). A lymphoma composed of immature small to medium-sized precursor lymphoid cells (lymphoblasts). "Similarly, complete loss of HDAC1 and HDAC2 in thymocytes results in a block in T cell development, while gradual loss of HDAC activity induces lymphoblastic lymphoma." (PMID 40175628, 2025).
mesothelioma (1 paper, 2015). A usually malignant and aggressive neoplasm of the mesothelium which is often associated with exposure to asbestos. "Intriguingly, in contrast to our data for transient HDAC2 knockdown, the constitutively HDAC2-deficient mesothelioma cell lines were more resistant to mocetinostat." (PMID 25970771, 2015). "As predicted, HDAC2 expression was low in BAP1 null mesothelioma cell lines and overall showed a tight correlation with BAP1 expression status." (PMID 25970771, 2015). "As BAP1 depletion had a profound effect on the HDAC2/HDAC1 expression ratio in MSTO-211H cells, we next examined the relationship between endogenous HDAC2 and BAP1 mutation status in a panel of established mesothelioma cell lines." (PMID 25970771, 2015). "Lastly, we assessed the relative HDAC inhibitor sensitivity of three established mesothelioma cells with constitutively low HDAC2 expression together with the MSTO-211H cells that retain high HDAC2 expression." (PMID 25970771, 2015). "Indeed we find that HDAC2 appears more important than HDAC1 in maintaining viability of the BAP1 positive mesothelioma cell line MSTO-211H." (PMID 25970771, 2015). "However, other established mesothelioma cell lines with low endogenous HDAC2 have adapted to become more resistant to HDAC inhibition." (PMID 25970771, 2015). "Interestingly, somatic BAP1 mutation is reported to be more common in current or ex-smokers who develop mesothelioma and could conceivably compound HDAC2 instability in response to cigarette smoke." (PMID 25970771, 2015). "Both HDAC1 and HDAC2 were expressed in the normal mesothelial MeT-5A cells, and HDAC1 was expressed at varying levels in the mesothelioma cell lines." (PMID 25970771, 2015).
metastatic prostate carcinoma (1 paper, 2022). A carcinoma that arises from the prostate gland and has spread to other anatomic sites. "In metastatic prostate cancer, an expanded HRD panel included patients with mutations to BRCA1, BRCA2, ATM, FANCA, CHEK2, PALB2, NBN, or HDAC2." (PMID 35205643, 2022).
mismatch repair deficiency (1 paper, 2022). "A number of synthetically lethal therapeutic opportunities arise on the basis of ARID1A mutations and mismatch repair deficiency, utilizing inhibitors of PARP1, HDAC2/6, Aurora kinase A, CKD4/6, or PI3K/Akt." (PMID 36078038, 2022).
mood disorder (1 paper, 2013). A cognitive disorder a disturbance in which the person's mood is hypothesized to be the main underlying feature. "Together, this study demonstrates that selective inhibition of HDAC1 and HDAC2 in mice modulates transcription in mood circuits and alters relevant behaviors, and may be a viable mechanism for the development of clinical mood disorder treatments." (PMID 23967191, 2013). "Our current findings stand as supportive evidence that selective inhibition of HDAC1 and HDAC2 results in beneficial changes in neuroplasticity and may be a novel target for mood disorder therapy." (PMID 23967191, 2013). "To further investigate the mechanism of HDAC inhibition in the underpinnings and treatment of mood disorders, we identified from the literature Cpd-60 (Compound 19, also published as Compound 60), a benzamide-based, subclass selective inhibitor of HDAC1 and HDAC2." (PMID 23967191, 2013).
nasal polyps (1 paper, 2016). "Related with CRS, we have previously shown that HDAC2 is elevated in nasal polyps, suggesting that they may serve as potential targets of treatment and that TSA inhibits extracellular matrix production in nasal polyps." (PMID 27571418, 2016).
ovarian serous carcinoma (1 paper, 2019). "In summary, this is the first study to investigate a molecular link connecting USP5, HDAC2, and p27 in ovarian serous carcinomas." (PMID 31727867, 2019). "In ovarian serous carcinomas tissues, a positive correlation was observed between the protein expression of USP5 and HDAC2." (PMID 31727867, 2019). "Pearson correlation analysis revealed that HDAC2 protein expression was positively correlated with USP5 protein expression, and negatively correlated with p27 protein expression in ovarian serous carcinomas tissues (P<0.0001)." (PMID 31727867, 2019). "HDAC2 protein was positively correlated USP5 protein, and negatively correlated with p27 protein in ovarian serous carcinomas tissues." (PMID 31727867, 2019).
pancreatitis (1 paper, 2025). Inflammation of the pancreas. "The involvement of HDAC2 in pancreatitis has garnered research interest due to its role in inflammation and pain modulation." (PMID 40337468, 2025). "We hypothesize that HDAC2 is highly expressed in the spinal cord during pancreatitis and contributes to pain through neural conduction inhibition." (PMID 40337468, 2025).
papilloma (1 paper, 2013). A benign epithelial neoplasm that projects above the surrounding epithelial surface and consists of villous or arborescent outgrowths of fibrovascular stroma. "In particular, the impaired activity of the Sin3A co-repressor complex and the concomitant overexpression of the c-Myc in HDAC1- but not HDAC2-deficient papillomas provide strong evidence for crucial function for Sin3A and HDAC1 as a negative regulator of the proto-oncogene c-Myc." (PMID 24240174, 2013).
parasite infection (1 paper, 2021). "HDAC2, a histone decrotonylase, was found to be significantly increased, which might be the executor of histone Kcr after parasite infection." (PMID 34322124, 2021).
post-traumatic stress disorder (1 paper, 2024). An anxiety disorder precipitated by an experience of intense fear or horror while exposed to a traumatic (especially life-threatening) event. "A recent study by Sun and colleagues reproducing an ELS rat model of post-traumatic stress disorder (PTSD) using a maternal separation (MS) protocol and a subsequent single prolonged stress (SPS) procedure examined H3K9 acetylation (H3K9ac), HDAC2, and BDNF levels in the hippocampus." (PMID 39457754, 2024).
preeclampsia (1 paper, 2019). Preeclampsia is a hypertensive disorder of pregnancy that is characterized by new-onset hypertension with proteinuria presenting after 20 weeks of gestation, and depending on mild or severe forms may initially present with severe headache, visual disturbances, and hyperreflexia. "Upregulated placental miR-299 in preeclampsia suppressed migration and invasion of trophoblasts via targeting histone deacetylase 2 (HDAC2)." (PMID 31671866, 2019).
proteinopathies (1 paper, 2020). "Therefore, it is more convincing that only HDAC1, but not HDAC2, is affected by nuclear TDP‐43 mislocalization, thus contributes to TDP‐43 proteinopathies." (PMID 32449313, 2020).
renovascular hypertensive (1 paper, 2021). "In addition, HDAC2 and HDAC8 expression levels are upregulated in renovascular hypertensive rats, while sodium valproate, a non-specific HDAC inhibitor, attenuates cardiac remodeling, confirming the involvement of HDAC2 and HDAC8 in cardiac remodeling." (PMID 33959033, 2021).
Rubinstein-Taybi syndrome (1 paper, 2024). A rare malformation syndrome characterized by congenital anomalies (microcephaly, specific facial characteristics, broad thumbs and halluces and postnatal growth retardation), short stature, intellectual disability and behavioral characteristics. "We performed whole exome sequencing (WES) for a patient (#249) clinically diagnosed with the chromatinopathy Rubinstein-Taybi syndrome (RSTS) but negative for mutations in RSTS genes, identifying a de novo frameshift variant in HDAC2 gene." (PMID 38753158, 2024).
sarcoidosis (1 paper, 2022). Sarcoidosis is a multisystemic disorder of unknown cause characterized by the formation of immune granulomas in involved organs. "Higher GR-α expression and lower HDAC2 expression in patients with sarcoidosis and COP compared with those in IPF patients has been previously reported, and we highlight the importance of GR-β/GR-α in corticosteroid-insensitive IPF." (PMID 35865549, 2022). "Correlations between radiographic deterioration and staining findings (neutrophil counts, IL-17, GR-β, GR-α, GR-β/GR-α, HDAC2) in ILDs (COP, sarcoidosis and IPF in combination) and IPF subgroup." (PMID 35865549, 2022). "In the present study, we have shown that in lung tissues from IPF patients, there was greater expression of IL-17 with up-regulated GR-β level and increased neutrophil infiltration compared to tissues from sarcoidosis and COP patients However, GR-α and HDAC2 expression were not different." (PMID 35865549, 2022).
scrapie (1 paper, 2023). A fatal disease of the nervous system in sheep and goats, characterized by pruritus, debility, and locomotor incoordination. "Therefore, the upregulation of HDAC2 observed in clinical scrapie sheep could contribute to the decrease in 5mC and 5hmC levels." (PMID 36675131, 2023).
seminoma (1 paper, 2024). A radiosensitive malignant germ cell tumor found in the testis (especially undescended), and extragonadal sites (anterior mediastinum and pineal gland). "Utilizing the SCENIC analysis on the non-seminoma tumor cells, we observed heightened activity of transcription factors quintessential for pluripotency maintenance, notably NANOG, POU5F1, and HDAC2, within the EC subset." (PMID 39528470, 2024).
Splenomegaly (1 paper, 2016). Abnormal increased size of the spleen. "To determine how the lack of Hdac1 and Hdac2 in B cells impacts Eμ-myc tumorigenesis, we analysed 8-week old mice by first measuring spleen weight, since Eμ-myc mice typically have splenomegaly." (PMID 27886239, 2016).
systemic sclerosis (1 paper, 2022). A chronic disorder, possibly autoimmune, marked by excessive production of collagen which results in hardening and thickening of body tissues. "A study of histone modification in systemic sclerosis (SS) patients showed that global acetylation of histone H4 was upregulated in B cells, while HDAC2 and HDAC7 were significantly downregulated." (PMID 35274786, 2022).
teratoma (1 paper, 2020). A non-seminomatous germ cell tumor characterized by the presence of various tissues which correspond to the different germinal layers (endoderm, mesoderm, and ectoderm). "Importantly, immunoexpression of these HDACs was particularly high in cisplatin-exposed metastatic samples, with 10/14 (71.4%) and 13/14 (92.9%) tumors with strong immunoexpression of HDAC1 and HDAC2, respectively (including 4/6 and 6/6 of non-teratoma cases, specifically)." (PMID 33050470, 2020).
thymic epithelial tumors (1 paper, 2023). "In this study we attempt the first comprehensive evaluation of six class I (HDAC1, HDAC2, HDAC3) and II HDACs (HDAC4, HDAC5, HDAC6) expression patterns in thymic epithelial tumors (TETs), with the aim of identifying their possible association with a number of clinicopathological parameters." (PMID 36901692, 2023).
thymic tumors (1 paper, 2025). "Notably, T cell-specific deletion of Hdac1 in non-ALK-transgenic mice also induced thymic tumors in approximately a quarter of mice at older ages, whereas no signs of malignant transformation were observed in thymi of mice with a deletion of Hdac2." (PMID 40175628, 2025).
thyroid tumor (1 paper, 2017). A benign or malignant neoplasm affecting the thyroid gland. "A previous study has indicated that CBX7 overexpression enhanced E-Cadherin activity by interacting with HDAC2 and inhibiting its activity on the E-cadherin promoter in thyroid tumors." (PMID 28388562, 2017).
tongue cancer (1 paper, 2018). A malignant neoplasm affecting the tongue. "HDAC2, TBP, and EP300 scored ≥10 on Maximal Clique Centrality (MCC) in STEM profile 11 and were overexpressed in human tongue cancer samples." (PMID 30135512, 2018).
tongue SCC (1 paper, 2021). "Additionally, high HDAC-2 expression, in terms of intense staining intensity, has been significantly correlated with muscular invasion and advanced depth of invasion in mobile tongue SCC cases." (PMID 33799478, 2021).
trichorhinophalangeal syndrome type I (1 paper, 2021). An autosomal dominant malformation syndrome caused by mutations in TRPS1 characterized by distinctive craniofacial and skeletal abnormalities. "Similarly, trichorhinophalangeal syndrome type I (TRPS1) functions as a scaffold protein involved in the USP4-induced stabilization of HDAC2 through bringing them together to form the TRPS1-USP4-HDAC2 complex." (PMID 33681193, 2021).
uterine cancer (1 paper, 2021). Primary or metastatic malignant neoplasm involving the uterine corpus and/or the cervix. "In line with our report, it has been shown that SAHA can down-regulate HDACs class I (HDAC2 and 3) and class II (HDAC7) resulting in p21WAF1 upregulation and apoptosis induction in uterine cancer." (PMID 34319031, 2021). "In uterine cancer, it has been reported that SAHA efficiently suppresses MES-SA uterine sarcoma cell growth by down-regulation of HDACs class I (HDAC2 and 3) and class II (HDAC7)." (PMID 34319031, 2021).
Ventricular arrhythmia (1 paper, 2025). "In addition, overexpression of HDAC2 in hypertrophic myocardium caused increased susceptibility to ventricular arrhythmias." (PMID 40497340, 2025).
vitiligo (1 paper, 2021). Generalized well circumscribed patches of leukoderma that are generally distributed over symmetric body locations and is due to autoimmune destruction of melanocytes. "The hub genes of vitiligo melanocytes include CDK1, HSP90AA1, AKT1, BCL2L1, HDAC2, HELLS, and KIF23." (PMID 33790887, 2021).
cancer (275 papers, 2006 to 2026). A tumor composed of atypical neoplastic, often pleomorphic cells that invade other tissues. "These interactions suggest a substantial contribution of the native site 2 in KBTBD4R313PRR to HDAC2 recruitment, demonstrating additional surface complementarity outside the cancer hotspot mutation site." (PMID 40175372, 2025). "HDACs, including HDAC2, are involved in epigenetic regulation and have been implicated in cancer cell survival and proliferation by modifying chromatin structure." (PMID 41224124, 2025). "Histone deacetylase 2 (HDAC2) has been linked to numerous biological processes, including inflammation, cancer initiation and progression, cell signaling, cellular proliferation, and gene expression control." (PMID 39619695, 2024). "We identified BMI1, MYC, NANOG, and OCT3/4 (POU5F1 gene) pluripotency markers as the most prominent transcription factors associated with HDAC2 gene expression, highly supporting HDAC2’s association with cancer stemness." (PMID 39063083, 2024). "Specifically, statins induces SL in cancer cells with BRCA1 mutations when coupled with the inhibition of HDAC2, a histone deacetylase involved in epigenetic regulation." (PMID 39217242, 2024). "Among them, the most significant downregulated DEG was HDAC2, which encodes histone deacetylase 2, a transcription factor capable of inducing inflammatory gene expression in CAFs and supporting carcinoma growth in PDAC." (PMID 38798691, 2024). "As such, comprehending the precise mechanisms underlying the functions of Histone Deacetylase 2 (HDAC2) in cancer is a crucial stride towards devising innovative therapeutic approaches for cancer management." (PMID 37495623, 2023). "HDAC1 and HDAC2 are associated with various cellular events responsible for cancer growth and development." (PMID 36681835, 2023). "Sex-determining region Y-box-containing TF2, a marker of cancer stemness, was associated with HDAC2." (PMID 36968022, 2023). "Using a dataset of 594 CRC patients/samples from the TCGA Pan Cancer Atlas, we looked at the percentage of alterations present in HDAC2, CIITA, and B2M based on mutations, mRNA expression levels, structural variants, and amplifications." (PMID 37046620, 2023). "One year later, another study demonstrated the same results, since the over-expression of HDAC-2 was positively associated with lymph node infiltration, undifferentiated cancer cells, and a worse clinical outcome." (PMID 36294811, 2022). "As the most important deacetylases involved in epigenetic regulation, HDAC2 is closely associated with the occurrence and development of cancers." (PMID 34365463, 2021). "Genes upregulated in association with SNVs in their 3′ UTR included HDAC2, which regulates chromatin plasticity and is frequently deregulated in cancer." (PMID 33554123, 2021). "Our results indicate that the deacetylase HDAC2, which is highly expressed in cancer and associated with tumor de-differentiation and invasion, was dramatically reduced." (PMID 32331482, 2020). "HDAC2 expression was highly decreased, in agreement with it being highly expressed in cancer, and its functions being associated with tumor de-differentiation and invasion." (PMID 32331482, 2020). "Previous studies have shown that increased activity of HDAC2 is associated with cancers, diverse neurodegenerative diseases, and neural toxicity." (PMID 31627491, 2019). "Future studies will examine how HDAC2 expression, microbiota, and SCFAs are linked and how this affects histone crotonylation over specific genes and cancer progression in the colon." (PMID 29317660, 2018). "In this study, we tried to discover the anti-cancer effect of RA on PCa, along with its underlying mechanism associated with HDAC2 inhibition and apoptosis induction." (PMID 30453545, 2018). "HDAC2 is known to have a role in cell cycle dysregulation in cancer; it is highly expressed in PDAC and associated with resistance to therapy and apoptosis." (PMID 27894105, 2017).